IFNG (interferon gamma)
Diseases named in the same sentence as IFNG in open-access papers (continued):
Sharing a sentence is not in itself a finding about the gene and the disease.
ependymoma (3 papers, 2017 to 2023). A WHO grade II, slow growing tumor of children and young adults, usually located intraventricularly. "We also observed significant upregulation of pro-inflammatory cytokines IFNα and IFNγ in both LGGs and craniopharyngiomas when compared with either MBs or ependymomas (Bonferroni-corrected p < 0.05)." (PMID 37492101, 2023).
Fabry disease (3 papers, 2022 to 2024). Fabry disease (FD) is a progressive, inherited, multisystemic lysosomal storage disease characterized by specific neurological, cutaneous, renal, cardiovascular, cochleo-vestibular and cerebrovascular manifestations. "The plasma and or renal biopsy samples from the mouse model of Fabry disease showed higher levels of Gb3, complement components (e.g., C3 and iC3b), and IFNγ." (PMID 37189685, 2023). "Patients with Fabry disease also demonstrate an increase in T cell subsets and increased circulatory levels of pro-inflammatory cytokines, such as TNFα, IFNγ, IL1α, IL1β, IL6, and IL17." (PMID 39596318, 2024). "Serum, plasma, PBMCs, and several of the immune cells that include MOs, DCs, and NK cells have shown massive production of pro-inflammatory cytokines (e.g., IFNγ, TNF α, IL1β, and IL6) in patients with Fabry disease." (PMID 37189685, 2023).
fertility disorders (3 papers, 2008 to 2011). "Interferon-gamma, IL-12 and GM-CSF were found to be elevated in inc-stimulated cervical cells and PBMCs of CT-positive fertile women compared to CT-positive women with fertility disorders and controls (P < 0.05)." (PMID 19397832, 2009). "Interferon-gamma secreting cells and mRNA expression in inc-stimulated cervical and peripheral CD4 positive T cells were significantly higher (P < 0.05) in CT positive fertile women compared to CT-positive women with fertility disorders." (PMID 19397832, 2009).
intestinal cancer (3 papers, 2023 to 2024). "We demonstrated that blocking IFNγ in vivo fully rescues aging-associated intestinal phenotypes and loss of regeneration, elevating IFNγ as a very promising therapeutic target for the treatment of complications of human aging-associated intestinal diseases, including intestinal cancer." (PMID 37777550, 2023). "In this study, we demonstrate that high expression of the NKG2D receptor enhances the production of IFNγ in a mouse model of intestinal cancer and that KLRK1 expression in primary CRC patients strongly correlates with the expression of genes associated with an IFNγ response." (PMID 36980678, 2023).
kidney injury (3 papers, 2012 to 2024). Trauma to the kidney. "In response to noxious stimuli, the innate immune system reacts by engaging and activating adaptive immune cells, and activated T-lymphocytes can secrete TNF -α, IL-17α, and interferon-gamma (IFN-γ), all of which also contribute to elevated blood pressure and kidney injury." (PMID 39311633, 2024).
macular holes (3 papers, 2023 to 2025). A hole in the macula of the retina. "In the macular holes with high myopia, the levels of the inflammatory cytokines C-C motif chemokine ligand 2 (CCL2), C-X-C motif chemokine ligand 10 (CXCL10), and interferon-gamma (IFNG) in the vitreous are significantly elevated." (PMID 40657400, 2025).
Meniere disease (3 papers, 2022 to 2025). A disease of the inner ear (labyrinth) that is characterized by fluctuating sensorineural hearing loss; tinnitus; episodic vertigo; and aural fullness. "Distinct cytokine profiles (elevated TNF-α and Interferon-gamma (IFN-γ), reduced ENA-78) have been observed in Meniere’s disease patients compared to those with vestibular migraine." (PMID 41306961, 2025).
morbid obesity (3 papers, 2021 to 2022). An excess of body weight, normally defined as an individual with a body mass index greater than 35 or a body weight greater than one hundred percent of ideal body weight. "It was previously reported that the activity of peripheral blood mononuclear cells (PBMCs) in morbid obesity is blunted, as reflected by reduced IFNγ and the monocyte chemotactic protein-1 (MCP-1), but weight loss is capable of restoring the ability of stimulated PBMCs to produce MCP-1 and IFNγ." (PMID 35062740, 2022).
muscular dystrophy (3 papers, 2019 to 2025). Muscular dystrophy (MD) refers to a group of more than 30 genetic diseases characterized by progressive weakness and degeneration of the skeletal muscles that control movement. "Furthermore, a previous study reported that the suppression of the interferon-gamma pathway in muscular dystrophy could reduce muscle damage." (PMID 35683408, 2022).
onchocerciasis (3 papers, 2021 to 2022). Onchocerciasis is a form of filariasis, caused by the parasitic worm Onchocerca volvulus, transmitted by the black fly. "Noteworthy, when peripheral blood mononuclear cells from onchocerciasis patients were stimulated with an O. volvulus antigen, they produced significantly less interferon-gamma (IFN-γ) and IL-5 compared to healthy controls." (PMID 34449738, 2021).
Osteopenia (3 papers, 2019 to 2025). Osteopenia is a term to define bone density that is not normal but also not as low as osteoporosis. "Overall, our data indicate that osteopenia during M. avium infection depends on IFNγ production, which mediates the upregulation of genes related to osteoclast formation and activity." (PMID 37153579, 2023). "Together, the data suggest that osteopenia during M. avium infection requires both IFNγ and TNFα." (PMID 37153579, 2023).
penile cancer (3 papers, 2020 to 2023). A primary or metastatic malignant neoplasm that affects the penis. "IPA identified potential upstream regulators that explain the transcriptional changes of human penile cancer, which included activated targets by pro-inflammatory factors such as TNF, CSF2, IFNγ, IL1B, and inhibited targets by TGFβ1." (PMID 32358507, 2020).
peripheral nerve injury (3 papers, 2016 to 2021). Injury to a peripheral nerve. "Further studies showed that in contrast to CD8+ αβ T cells, B cells, NK cells, and macrophages, CD4+ αβ T cells were selectively activated by dendritic cells and polarized to IFNγ-positive, inflammatory Th1 cells in peripheral lymphoid organs, such as the spleen, after peripheral nerve injuries." (PMID 29544518, 2018).
Peritoneal Fibrosis (3 papers, 2014 to 2023). Disorder characterized by a wide range of structural changes in PERITONEUM, resulting from fibrogenic or inflammatory processes. "Thus, TGFβ1 promotes peritoneal fibrosis and dysfunction, PDGF-B promotes angiogenesis, IL-6 and its soluble receptor (sIL-6R) control the pattern of leukocyte recruitment during peritoneal inflammation and the IFNγ/TNFα combination promotes mesothelial cell apoptosis." (PMID 24599047, 2014).
periventricular leukomalacia (3 papers, 2012 to 2024). Periventricular leukomalacia (PVL) is a brain injury disorder characterized by the death of the white matter of the brain due to softening of the brain tissue. "For example, LPS and IFNγ are thought to be involved in brain disorders such as those arising from perinatal intrauterine infections that cause various brain injuries ranging from periventricular leukomalacia (PVL) with permanent motor impairment to adult-onset neuropsychiatric disorders." (PMID 24244457, 2013).
PFAPA syndrome (3 papers, 2010 to 2022). An auto inflammatory syndrome characterized by recurrent febrile episodes associated with aphthous stomatitis, pharyngitis and cervical adenitis. "Elevated levels of the IFNγ-induced chemokines CXCL9/MIG and CXCL10/IP10 in the absence of Th2- and Th17-associated cytokines indicated that components of a Th1-type inflammatory response coincide with fever in PFAPA syndrome." (PMID 20819226, 2010).
plasmacytoma (3 papers, 2018 to 2022). Plasmacytoma is a localized mass of neoplastic monoclonal plasma cells that represents approximately 5% of all plasma cell neoplasms. "For other tumor cell types, including the MOPC315 plasmacytoma cell line used in the present study, the tumor cells do not themselves express MHC class II, even in the presence of interferon gamma (IFN-γ)." (PMID 30083157, 2018).
polycystic ovary syndrome (3 papers, 2021 to 2025). A disorder that manifests as multiple cysts on the ovaries. "In mouse models of polycystic ovary syndrome, treatment with DHEA resulted in increased production of cytokines such as serum TNFα, IL-6, IL12p70, and IFNγ." (PMID 37268990, 2023).
psychological distress (3 papers, 2022 to 2025). "Pro-inflammatory plasma cytokines, which showed a correlation with higher psychological distress, included interleukin (IL)-2, IL-12, tumor necrosis factor-α (TNF-α), and interferon-gamma (IFN-γ)." (PMID 40151707, 2025).
rheumatic heart disease (3 papers, 2017 to 2022). An autoinflammatory condition following an infection with Group A Beta Hemolytic Streptococcus (GABHS), in which the heart is attacked by antibodies formed in reaction to a recent GABHS infection. "For example, group G Streptococcus induced an autoimmune carditis mediated by IL-17A and interferon gamma in the Lewis rat model of rheumatic heart disease." (PMID 32733424, 2020). "In fact, it has been suggested that Th1 and Th17 have been implicated in the autoimmune process leading to the formation of heart lesions in rheumatic heart disease (RHD) and that Th17 T cells expressing IFNγ may be pathogenic." (PMID 28414746, 2017).
Toxocara infection (3 papers, 2015 to 2025). "Increased number of eosinophils, increased concentrations of total immunoglobulin E (IgE), and increased levels of interleukin (IL)-4, IL-6, IL-5, IL-10, IL-13, and interferon-gamma (IFN-γ) were reported in peripheral blood of patients with systemic signs of Toxocara infection." (PMID 35419376, 2022).
tuberculous peritonitis (3 papers, 2020 to 2024). A form of peritonitis seen in patients with tuberculosis, characterized by lesion either as a miliary form or as a pelvic mass on the peritoneal surfaces. "According to the World Gastroenterology Organisation Global Guidelines for digestive tract tuberculosis, interferon-gamma assay such as T-SPOT is a highly sensitive test for the diagnosis of tuberculous peritonitis." (PMID 38771503, 2024). "Measurement of peritoneal fluid interferon-gamma concentration may be a useful tool for diagnosis of tuberculous peritonitis." (PMID 39845238, 2024).
uremia (3 papers, 2023 to 2025). A clinical syndrome associated with the retention of renal waste products or uremic toxins in the blood. "Impaired T-lymphocyte function constitutes the main deficit: uremia reduces proliferative activity and disrupts the synthesis of key cytokines, particularly interferon-gamma (IFN-γ), which is a central marker in TB immunodiagnostics (IGRAs)." (PMID 41574365, 2025).
Ureteral obstruction (3 papers, 2015 to 2016). Obstruction of the flow of urine through the ureter. "Three days after ureteral obstruction, we intravenously transferred M0, M (IFNγ + LPS) or M (IL4 + IL13) and assessed the degree of inflammation and fibrosis 4 days later, as displayed in the experimental design." (PMID 27621813, 2016).
urinary tract infection (3 papers, 2021 to 2025). "HbSS subjects with asymptomatic urinary tract infections had elevated plasma levels of interferon gamma (IFN-γ) and interleukin (IL)-10." (PMID 34239376, 2021).
urothelial carcinoma (3 papers, 2021 to 2025). A malignant neoplasm derived from the transitional epithelium of the urinary tract (urinary bladder, ureter, urethra, or renal pelvis). "We conclude that CGB7 is significantly associated with blunted interferon gamma signaling and is specifically and significantly associated with decreased CD8+T cell infiltration in the urothelial carcinoma cohorts investigated." (PMID 40501795, 2025).
acute alcoholic hepatitis (2 papers, 2016 to 2020). "In alcoholic hepatitis, TNFα/IFNγ induces FAT10 expression via NFκB and/or STAT3 pathways." (PMID 32630199, 2020). "The pathway that increases FAT10 expression includes TNFα and IFNγ, followed by NFκB and STAT3, all of which were up-regulated in alcoholic hepatitis." (PMID 32630199, 2020). "In summary, FAT10 was only found in human and mouse liver specimens and plays critical role in the development of alcoholic hepatitis via NFκB and/or STAT3 pathways induced by TNFα/IFNγ." (PMID 32630199, 2020).
acute monocytic leukemia (2 papers, 2018 to 2021). Acute monoblastic leukemia (AML-M5), is one of the most common subtypes of acute myeloid leukemia (AML) that is either comprised of more than 80% of monoblasts (AML-M5a) or 30-80% monoblasts with (pro)monocytic differentiation (AML-M5b). "Interferon-gamma (IFNγ) can mediate induction of LRRK2 in acute monocytic leukemia THP-1 cells and human peripheral blood monocytes which is dependent on the ERK pathway." (PMID 34004238, 2021).
acute promyelocytic leukemia (2 papers, 2015 to 2023). An aggressive form of acute myeloid leukemia (AML), characterized by arrest of leukocyte differentiation at the promyelocyte stage, due to a specific chromosomal translocation t(15;17) in myeloid cells. "In acute promyelocytic leukemia cells, IFNG exhibit a synergistic effect with As203, regulating IRF-1 expression and apoptosis induction." (PMID 38002949, 2023).
Alcoholic cirrhosis (2 papers, 2013 to 2023). "Alcoholic cirrhosis promotes the progression of ALD via enhanced production of interferon-gamma, and a greater proinflammatory Th1 cell response has been identified found in the AH patients than in the alcoholic cirrhosis context." (PMID 37143126, 2023).
anterior uveitis (2 papers, 2022 to 2024). Inflammation of the iris and anterior chamber of the eye. "In humans with anterior uveitis, specific pro-inflammatory cytokines have been detected in aqueous humor (AH) including Interleukin (IL)-6, IL-8, IL-10, IL-13, IL-17, interferon-gamma (IFNγ), and tumor necrosis factor-alpha (TNFα)." (PMID 35998207, 2022).
apical periodontitis (2 papers, 2019 to 2024). "Additionally, active lesions can be clustered in groups presenting distinct patterns of IFNγ and IL-17 expression, suggesting that Th1/Th17 cytokines can drive apical periodontitis development independently." (PMID 31379856, 2019).
Ataxia (2 papers, 2018 to 2024). Ataxia refers to impaired coordination of voluntary muscle movement. "When IFNγ signaling is impaired, myeloid cell production of CXCL2 increases, which promotes brainstem inflammation and results in clinical ataxia." (PMID 30012158, 2018).
ataxia telangiectasia (2 papers, 2018 to 2022). Ataxia-telangiectasia is the association of severe combined immunodeficiency (affecting mainly the humoral immune response) with progressive cerebellar ataxia. "For example, fibroblasts from ataxia-telangiectasia (AT) patients demonstrated significantly higher levels of interferon-gamma genes and in AT-null mice, this effect appeared to be mediated by STING and result from accumulation of cytoplasmic DNA113." (PMID 30120226, 2018).
attention deficit-hyperactivity disorder (2 papers, 2020 to 2025). A disorder characterized by a marked pattern of inattention and/or hyperactivity-impulsivity that is inconsistent with developmental level and clearly interferes with functioning in at least two settings (e.g. at home and at school). "Nevertheless, both autism spectrum disorders (ASD) and attention deficit hyperactivity disorder (ADHD) are associated with increases in adaptive immune (T) cell cytokines, specifically Th2-like cytokines (IL-4, IL-6, and/or IL-10), or decreases in Th2-like cytokines (IL-2 and/or IFNγ)." (PMID 33424735, 2020).
bacterial vaginosis (2 papers, 2014 to 2021). Infection caused by bacterial overgrowth in the vagina. "In vitro studies indicate IFNγ is central to Chlamydia trachomatis (Ct) eradication, but its function may be compromised by anaerobes typically associated with bacterial vaginosis (BV), a frequent co-morbidity in women with Ct." (PMID 33912473, 2021).
blastoma (2 papers, 2020 to 2021). A malignant neoplasm composed of undifferentiated cells. "The QSOX2 gene encodes quiescin sulfhydryl oxidase 2, a member of the sulfhydryl oxidase/quiescin-6 (Q6) family (QSOX1), which are involved in the sensitization of neuro-blastoma cells for IFN-gamma (IFNG)-induced cell death." (PMID 34205581, 2021).
capillary leak syndrome (2 papers, 2015 to 2023). A syndrome characterized by leakage of intravascular fluids into the extravascular space. "Therefore, blocking IFNγ by CREKA-lipo-anti-IFNγ has the potential to prevent capillary leak syndrome and venous thromboembolism in cancer patients undergoing chemotherapy, which merits further studies." (PMID 37056922, 2023).
cardiac arrest (2 papers, 2015 to 2020). Cessation of breathing and/or cardiac function. "In muscle, similar differences between “cardiac arrest group” animals and “injury group” were also seen, along with marked increases in IL-18, IL-1α, IL-6, IFNγ, and MCP-1." (PMID 26635801, 2015). "In “cardiac arrest group” animals, the cytokine with the highest differential elevation relative to “injury group” animals was IFNγ." (PMID 26635801, 2015). "Furthermore, high levels of IFNγ were observed in the “cardiac arrest group” animals, while IFNγ was entirely absent from the “injury group” animals." (PMID 26635801, 2015).
cerebellar tumors (2 papers, 2016 to 2023). "As in vivo overexpression of IFNγ in the CNS during early development (when myelination normally takes place) causes confounding cerebellar tumours and maldevelopment, we instead turned to a simplified in vitro system." (PMID 36949514, 2023). "Ectopic expression of IFNγ during CNS development in mice results in cerebellar tumors that share the major molecular and pathological characteristics of human MB." (PMID 27174915, 2016).
clonorchiasis (2 papers, 2020 to 2021). Infection of the biliary passages with clonorchis sinensis, also called Opisthorchis sinensis. "TLR4 was involved in immune responses, including increased levels of tumor necrosis factor alpha and interferon gamma during clonorchiasis." (PMID 35127549, 2021).
cognitive disease (2 papers, 2020 to 2021). "Maternal inflammation leads to elevated pro-inflammatory cytokines such as IFN gamma (IFNγ) and interleukins (IL) 4, 5 and 6, and these are believed to mediate the effects of infection on fetal brain development and subsequent cognitive disease outcomes." (PMID 33288794, 2020).
diabetic cardiomyopathy (2 papers, 2014 to 2025). Diabetic cardiomyopathy is a disorder of the heart muscle in people with diabetes. "In contrast, its liver toxicity is linked to targets like IFNG and HMOX1, mainly through the diabetic cardiomyopathy pathway, potentially increasing risks due to overlapping pathways." (PMID 41155650, 2025).
disseminated tuberculosis (2 papers, 2013 to 2022). "Here, we report a patient with miliary tuberculosis who presented with a chief complaint of chronic diarrhea and fecal continence, with prior recent negative interferon-gamma release assay testing." (PMID 36277529, 2022).
gastric polyp (2 papers, 2017 to 2024). "Through the IVW method, we provided evidence of a causal association between monokine induced by interferon gamma (MIG) and gastric polyp (OR: 1.124, 95%CI: 1.046–1.207, p = 0.001)." (PMID 39439893, 2024).
Gaucher disease (2 papers, 2011 to 2022). Gaucher disease (GD) is a lysosomal storage disorder encompassing three main forms (types 1, 2 and 3), a fetal form and a variant with cardiac involvement (Gaucher disease - ophthalmoplegia - cardiovascular calcification or Gaucher-like disease). "These analyses implicate IFNγ-regulated pro-inflammatory and IL-4-regulated anti-inflammatory networks in differential disease progression with implications for understanding the Gaucher disease course and pathophysiology." (PMID 21223590, 2011).